GRPR (gastrin releasing peptide receptor)
Diseases named in the same sentence as GRPR in open-access papers (continued):
Sharing a sentence is not in itself a finding about the gene and the disease.
oral cancer (5 papers, 2016 to 2025). "GRPR was further used as a biomarker for surgical margin prediction in a murine orthotopic model of oral cancer and a strong expression of GRPR was observed uniformly in primary OSCC sections as compared to respective adjacent non-malignant region." (PMID 32651409, 2020). "Notably, TM1-IR680 conjugated with gastrin-releasing peptide receptor (GRPR)-targeting peptides enabled intraoperative visualization of tumor margins and lymphatic metastases in orthotopic oral cancer murine models." (PMID 40497859, 2025). "In this study, we used a GRPR-specific Alexa Fluor 750 (AF750) labeled BBN antagonist, AF750-6Ahx-Sta-BBN, to evaluate the expression of GRPR in OSCC and normal epithelial tissues by immunofluorescence, and the binding selectivity and affinity to human oral cancer cell line HSC-3 cells in vitro." (PMID 32651409, 2020). "One such target, Gastrin Releasing Peptide Receptor (GRPR) was selected for the study, and its binding peptide, TM1-IR680, was tested for its efficacy for surgical margin prediction in murine orthotopic model of oral cancer, derived from primary samples." (PMID 27827443, 2016).
prostate adenocarcinoma (5 papers, 2016 to 2024). "The uptake and internalization of [99mTc]Tc-DT11 alone or in an equimolar mixture with [99mTc]Tc-DB7 was directly compared by 1 h incubation at 37 °C in prostate adenocarcinoma PC-3 cells, endogenously co-expressing the human GRPR and NTS1R." (PMID 39339259, 2024). "In typical PCa cell lines such as PC-3 (bone metastasis of a grade IV PCa) it has been shown that there are severely upregulated GRPR, other PCa cell lines, whereas the LNCaP cell line (lymph node metastasis of a prostate adenocarcinoma) express the GRPR to a lower level." (PMID 35494646, 2022). "We were interested to investigate the effect of linker length on several biological features of resulting analogs, such as GRPR affinity, cell uptake, in vivo metabolic stability, and pharmacokinetics in mice bearing human GRPR-expressing prostate adenocarcinoma PC-3 xenografts." (PMID 32731473, 2020).
atopic dermatitis (4 papers, 2013 to 2025). "Previous research showed that block Nppb-GRPR signaling significantly reducing scratching behavior in atopic dermatitis model." (PMID 41451134, 2025). "Nevertheless, it is worth evaluating GRPr and NMBr antagonists in animal models of chronic itch such as atopic dermatitis and cholestasis." (PMID 23826298, 2013).
ovarian carcinoma (4 papers, 2003 to 2022). A malignant neoplasm originating from the surface ovarian epithelium. "Overexpression of the gastrin-releasing peptide receptor (GRP-R) has been documented in several human neoplasms such as breast, prostate, and ovarian cancer." (PMID 26897133, 2016). "The most studied GPCRs in the context of ovarian cancer are the somatostatin (SSTR1–5), cholecystokinin (CCKAR/CCKBR), gastrin-releasing peptide (GRPR), luteinizing hormone-releasing hormone (LHRHR) and neurotensin receptors (NTSR1/2)." (PMID 35625966, 2022). "Several receptors have been found to be upregulated in ovarian cancer tissues, including growth hormone releasing hormone receptor (GHRHR), GRPR, leucine-rich repeat-containing G-protein coupled receptor 5 (LGR5), oxytocin receptor (OXTR) and parathyroid hormone 2 receptor (PTH2R)." (PMID 35625966, 2022). "The PEO4 ovarian cancer cell line and H69 SCLC cell lines showed high expression of the GRPR." (PMID 12771999, 2003).
Anxiety (3 papers, 2012 to 2025). Intense feelings of nervousness, tension, or panic often arise in response to interpersonal stresses. "In addition, we have proposed that dysfunctions in GRPR expression and signaling might play a role in CNS disorders including anxiety, autism, memory dysfunction associated with neurodegenerative disorders, and brain tumors." (PMID 23251133, 2012). "As reviewed above, data from animal studies also consistently show that GRPRs in brain areas including the amygdala regulate memory related to fear and anxiety responses, raising the possibility that GRPR signaling plays a role in anxiety disorders." (PMID 23251133, 2012). "Below, we summarize relevant findings of selected studies focusing on GRPR regulation of memory, stress and anxiety responses, feeding, itching, and sexual behavior." (PMID 23251133, 2012). "However, an important difference between the two knockout lines is that GAD65 KO mice have enhanced both innate fear/anxiety and learned fear, while the GRPR KO mice have an enhancement specific to learned fear." (PMID 22312434, 2012). "On the other hand, whereas GRPR KO mice have normal anxiety, stathmin KO mice showed an impairment of innate fear, which could be in relation with the deficit observed during the acquisition of contextual fear conditioning." (PMID 22312434, 2012). "We interpret these findings to indicate that the increase in freezing observed in fear conditioning is due to differences in memory, but not in anxiety or pain sensitivity, confirming the behavioral phenotype of GRPR KO mice." (PMID 39580604, 2025).
benign prostatic hyperplasia (3 papers, 2021 to 2024). A non-cancerous nodular enlargement of the prostate gland. "The expression of the GRPR gene was assessed in fresh frozen specimens from 12 cases of PC and 6 cases of benign prostatic hyperplasia using Reverse Transcription-Polymerase Chain Reaction (RT-PCR) and in situ hybridization techniques." (PMID 38279185, 2024). "The elevated expression of GRPR in PC compared to benign prostatic hyperplasia presents a promising target for PC staging and monitoring." (PMID 38279185, 2024). "The findings revealed that GRPR was expressed in both PC and benign prostatic hyperplasia tissues." (PMID 38279185, 2024). "To this end, we evaluated and compared ex vivo binding of the GRPR- and PSMA-targeting radiopharmaceuticals [177Lu]Lu-NeoB and [177Lu]Lu-PSMA-617, respectively, to patient tissue sections obtained from benign prostatic hyperplasia (BPH), primary PCa and progressive CRPC lesions." (PMID 37719014, 2023). "GRPR overexpression gradually increases in prostatic carcinogenesis reaching from low-grade prostatic intraepithelial neoplasia (PIN) over high-grade PIN to low grade PC, whereas GRPR shows only little expression in normal prostate tissue in benign prostate hyperplasia and high grade PC." (PMID 33854977, 2021). "Binding of the GRPR- and PSMA-targeting radiopharmaceuticals [177Lu]Lu-NeoB and [177Lu]Lu-PSMA-617, respectively, was evaluated and compared on tissue sections of 20 benign prostatic hyperplasia (BPH), 16 primary PCa and 17 progressive castration-resistant PCa (CRPC) fresh frozen tissue specimens." (PMID 37719014, 2023).
lymph node metastases (3 papers, 2023 to 2024). "Four (67%) of six lymph node metastases were mild to strongly positive for GRPR expression." (PMID 36761980, 2023). "The expression of GRPR, PSMA, and NTR1 was evaluated in tissue sections of 34 specimens of PIN, 171 specimens of PCa, and 22 specimens of lymph node metastasis by performing immunohistochemistry staining." (PMID 38880858, 2024). "On one hand, our study suggested, for the first time, that expression differences of PSMA, GRPR, and NTR1 can reflect different PIN, PCa and lymph node metastasis." (PMID 38880858, 2024).
metastatic prostate carcinoma (3 papers, 2021 to 2025). A carcinoma that arises from the prostate gland and has spread to other anatomic sites. "Recent investigations into GRPR-targeted radionuclide therapy in the setting of metastatic prostate cancer have been promising." (PMID 35890071, 2022). "Moreover, a clinical trial has also recently been performed to assess the dosimetry and safety of the GRPR-antagonist RM2 labeled with Lu-177 for therapy of metastatic prostate cancer." (PMID 33801382, 2021). "Studies of peptides targeting the gastrin-releasing peptide receptor (GRPR), on the surface of localised and metastatic prostate cancers, are also underway." (PMID 41049848, 2025).
Obesity (3 papers, 2017 to 2020). Accumulation of substantial excess body fat. "A previous study identified in five patients with obesity heterozygous or hemizygous mutations in GRPR that were predicted functionally relevant." (PMID 32153512, 2020). "It is a hormone directly implicated in the regulation of food ingestion and satiety and, thus, a candidate to be associated with obesity (directly or by an alteration of a gene included in the pathway, such as GRPR)." (PMID 28489853, 2017). "In addition, we identified rare heterozygous missense variants in ADCY3 (p.G1110R), MYT1L (p.R807Q), ISL1 (p.I347F), LRP2 (p.R2479I, and p.N3315S) and a hemizygous missense variant in GRPR (p.L87M) (each in one patient), possibly contributing to the obesity phenotype in these patients." (PMID 32153512, 2020). "Four different missense mutations were detected in GRPR in five patients with obesity, while no mutations in this gene were found in controls (5/662 alleles vs 0/726 alleles; p = 0.0245)." (PMID 28489853, 2017). "Among those, the genes encoding the neuropeptide Y (NPY), two glutamate receptors (GRIK1, GRM7), the X-linked gastrin-peptide receptor (GRPR), and the organic anion transporter (SLCO4C1) are novel obesity candidate genes that may contribute to highly penetrant forms of familial obesity." (PMID 28489853, 2017). "A total of 10 shared co-expressed partners were identified in the analysis between our 4 novel strongest candidate genes (GRIK1, GRM7, GRPR and SLCO4C1) and the set of 15 obesity-related genes described in the literature." (PMID 28489853, 2017). "Interestingly, we found additional RSVs in patients in 4 of the selected genes (NPY, GRPR, SLCO4C1 and GRIK1) reinforcing their putative role in the pathophysiology of obesity." (PMID 28489853, 2017). "To further assess the possible implication of these strong candidate genes (GRIK1, GRM7, GRPR and SLCO4C1), we determined the co-expression patterns between them and 15 well-defined genes from the leptin-melanocortin pathway previously related to obesity." (PMID 28489853, 2017).
osteoarthritis (3 papers, 2021 to 2025). A noninflammatory degenerative joint disease occurring chiefly in older persons, characterized by degeneration of the articular cartilage, hypertrophy of bone at the margins and changes in the synovial membrane. "There are relatively few studies on the mechanism of role of LYRM4-AS1, and a recent report found that the beneficial effects of the bone marrow mesenchymal stem cell-derived exosomes on the pathogenesis of osteoarthritis through targeting the LYRM4-AS1/GRPR/miR-6515-5p signaling pathway." (PMID 37810780, 2023). "miR-6515-5p within exosomes isolated from bone marrow mesenchymal stem cells plays a crucial role in exerting a protective effect on osteoarthritis, which occurs through a regulatory axis involving lncRNA LYRM4-AS1 and GRPR." (PMID 40287741, 2025).
autism (2 papers, 2012 to 2024). Persistent deficits in social interaction and communication and interaction as well as a markedly restricted repertoire of activity and interest as well as repetitive patterns of behavior. "As one of the potential pathogenic genes of autism, GRPR has received increasing attention in the field of neurological research." (PMID 38536552, 2024). "Although a subsequent study investigating two polymorphic sites in the second exon of the GRPR gene in patients did not support the GRPR as a candidate locus for autism, more recently a possible role of C6S and L181F mutations of the GRPR gene in GRPR function and ASD was found in two patients." (PMID 23251133, 2012). "The first evidence suggesting that the GRPR might be a candidate gene in autism spectrum disorders (ASD) was the finding of a translocation breakpoint on the X chromosome in the first intron of the GRPR gene in a patient with autism accompanied by mental retardation and epilepsy." (PMID 23251133, 2012). "Therefore, we hypothesize that GRPR could be upregulated in ASD mice exposed to MIA and exacerbate autism-like behavior by activating the PI3K-AKT/mTOR signaling pathway." (PMID 38536552, 2024).
autism spectrum disorder (2 papers, 2012 to 2025). A spectrum of developmental disorders that includes autism, and Asperger syndrome. "The inhibition of GSK-3β via targeting the IL-6-mediated PI3/AKT/mTOR pathway decreases neural apoptosis and affects autism spectrum disorder via GRPR." (PMID 40843259, 2025). "IL-6 activates other signaling pathways, such as the PI3K/AKT/the mammalian target of rapamycin (mTOR) glycogen synthase kinase-3 beta (GSK-3β) and gastrin-releasing peptide (GRP) receptor (GRPR) pathways, in hippocampal neurons of mice with autism spectrum disorder." (PMID 40843259, 2025).
brain tumor (2 papers, 2012 to 2023). "In addition, some alterations in GRP or GRPR expression or function have been described in patients with neurodegenerative, neurodevelopmental, and psychiatric disorders, as well as in brain tumors." (PMID 23251133, 2012).
cognitive deficits (2 papers, 2007 to 2018). "Thus, GRPR agonistic changes may ameliorate the cognitive impairments." (PMID 29463009, 2018).
colorectal cancer (2 papers, 2021 to 2023). A primary or metastatic malignant neoplasm that affects the colon or rectum. "Gastrin-releasing peptide receptors (GRPr) are a subtype of the bombesin receptor family, overexpressed in several malignancies, such as lung, prostate, breast, gastric and colorectal carcinomas." (PMID 37376181, 2023). "Gastrin-release Pepper (GRP) and its receptor (GRPR) are abnormally highly expressed in colorectal cancer, while CKB is significantly higher in cell lines expressing GRP/GRPR." (PMID 34354842, 2021).
contact dermatitis (2 papers, 2020 to 2023). An inflammatory skin condition caused by direct contact between the skin and either an irritating substance or an allergen. "Similar to contact dermatitis as previously reported, 6 upregulation of GRP and GRPR directly indicates the enhancement of the GRP‐GRPR system under psoriatic itch." (PMID 32584520, 2020).
depression (2 papers, 2019 to 2020). "The administration of fluoxetine and a reduction in either 5-HT2AR or GRPR is associated with a reduction in depression behavior." (PMID 32047449, 2019). "Interestingly, GRPR has also been implicated in psychiatric disorders like depression, suggesting that the hemizygous GRPR variant contributes to the severe depression seen in our patient." (PMID 32153512, 2020). "Our findings provide additional research ideas to explore the pathogenesis of targeting GRPR signaling in depression." (PMID 32047449, 2019). "This study also provides in vitro experimental evidence of the interaction between 5-HT2aR and GRPR, which may play an important role in the pathogenesis of depression." (PMID 32047449, 2019). "Accumulating evidences indicate that gastrin-releasing peptide receptor (GRPR) may contribute to the pathophysiology of depression." (PMID 32047449, 2019). "Our study enhances the understanding of the involvement of GRPR in depression." (PMID 32047449, 2019). "By performing coimmunoprecipitation and double immunofluorescence staining, we confirmed the interaction between 5-HT2aR and GRPR in vitro, which may provide new ideas for the treatment of depression." (PMID 32047449, 2019). "However, the mechanism of the involvement of GRPR in the progression of depression remains unclear." (PMID 32047449, 2019).
immune deficiency (2 papers, 2019). "The biodistribution of 111In-SB3 and 111In-SB4 was studied in severe combined immune deficiency (SCID) mice bearing human PC-3 xenografts expressing the GRPR." (PMID 30871262, 2019).
medulloblastoma (2 papers, 2012 to 2021). A malignant, invasive embryonal neoplasm arising from the cerebellum. "On immunohistochemical analysis, as well as PCR studies, all three medulloblastoma cell lines possessed GRPR and GRPR mRNA." (PMID 34539578, 2021). "Despite the presence by both PCR and immunohistochemical studies of mGRPR and GRPR, respectively, in the three different medulloblastoma cell lines (DAOY, D283, ONS76), treatment of the cells with either Bn or GRP did not affect cell viability." (PMID 34539578, 2021). "In two studies, three different medulloblastoma cell lines (DAOY, D283, ONS76) were examined for expression of GRPR by PCR and by immunohistochemistry." (PMID 34539578, 2021). "No studies have examined the signaling cascades of BnRs (GRPR, NMBR) in medulloblastomas." (PMID 34539578, 2021).
memory impairment (2 papers, 2007 to 2018). "The GRPR and its ligand GRP are also implicated in memory impairments in patients with AD, transgenic mouse models of AD, and psychiatric disorders." (PMID 29463009, 2018).
optic pathway glioma (2 papers, 2020 to 2021). Optic pathway glioma (OPG) is a benign tumor that develop along the optic nerve (chiasm, tracts, and radiations) characterized by impairment or loss of vision and may be accompanied by diencephalic symptoms such as reduced growth and alteration in sleeping patterns. "GRPR is a bombesin family receptor expressed in several tumors and especially in optic-pathway glioma." (PMID 34577572, 2021).
pancreatic adenocarcinoma (2 papers, 2024). "Previous research indicates that GRPR signaling induces transcription and DNA synthesis in human pancreatic adenocarcinoma cells and regulates Cox-2 mRNA expression in various tissues." (PMID 39768218, 2024).
renal cell carcinoma (2 papers, 2018 to 2021). "As a receptor for gastrin-releasing peptide (GRP), GRPR promotes renal cell carcinoma by activating ERK1/2 pathway together with GRP." (PMID 30466390, 2018).
Sepsis (2 papers, 2013 to 2021). Sepsis is defined as life-threatening organ dysfunction caused by a dysregulated host response to infection. "Recent studies have shown that selective GRPR antagonist (RC-3095) has anti-inflammatory effects on arthritis and sepsis models." (PMID 34568491, 2021). "Gastrin-releasing peptide receptor (GRPR) is linked to TLR4 signaling and antagonistic blockade of GRPR leads to limited protection from lethal sepsis." (PMID 24086587, 2013).
squamous cell carcinoma (2 papers, 2025). A carcinoma arising from squamous epithelial cells. "This experience supports extending GRPR-targeted diagnostics and therapeutics to other malignancies exhibiting GRPR overexpression, such as squamous cell carcinomas, warranting further investigation in this setting." (PMID 41266536, 2025). "This study aimed to evaluate GRPR expression in tumor samples obtained from patients with histopathologically confirmed squamous cell carcinomas of the head and neck and esophagus." (PMID 41266536, 2025).
triple-negative breast carcinoma (2 papers, 2019). An invasive breast carcinoma which is negative for expression of estrogen receptor (ER), progesterone receptor (PR), and human epidermal growth factor receptor 2 (HER2). "An in silico Kaplan Meier analysis revealed that GRK5 and GRPR overexpression reduces the distant metastasis free survival in triple-negative breast cancer (TNBC) patients." (PMID 31664083, 2019). "When examined in molecular subtypes, GRPR is over-expressed in 86.2% of luminal-A and 82.8% of luminal-B HER2 negative tumors while triple negative breast cancers and HER2-enriched phenotypes exhibit GRPR over-expression in only 7.8% and 21.3% of cases." (PMID 30645633, 2019).
xerostomia (2 papers, 2023 to 2025). Dryness of the mouth resulting from reduced salivary secretion. "Nevertheless, for mCRPC the clinical benefit of using [177Lu]Lu-RM2 is limited to patients who have high expression of GRPr and experienced xerostomia as a dose-limiting event after PSMA-targeted RLT." (PMID 38201600, 2023).
allergic conjunctivitis (1 paper, 2023). "In the present study, we analyzed the involvement of GRP/GRPR in the transmission of acute itchy eyes and did not analyze the effect of GRP/GRPR on pain in the trigeminal system or in pathological models of allergic conjunctivitis." (PMID 38098939, 2023).